PPP1R13L (protein phosphatase 1 regulatory subunit 13 like)
Diseases named in the same sentence as PPP1R13L in open-access papers (continued):
Sharing a sentence is not in itself a finding about the gene and the disease.
corneal opacities (1 paper, 2017). "The eyes in adult Ppp1r13l‐mutated mice are identified with severe corneal opacities, abnormalities of the anterior eye segment, and absence of meibomian glands." (PMID 28069640, 2017).
lymph node metastasis (1 paper, 2025). "According to the GSE26511 dataset, patients with lymph node metastasis exhibit higher PPP1R13L mRNA expression compared to those without metastasis." (PMID 40014097, 2025).
Obesity (1 paper, 2019). Accumulation of substantial excess body fat. "Twenty one target genes of NF-κB have shown strong association with obesity and the occurrence of GEM and PPP1R13L with known obesity related genes provides strong evidence to pick them as potential target genes." (PMID 31013288, 2019). "Except for two genes (GEM and PPP1R13L), all other 21 target proteins were found to be strongly associated with obesity." (PMID 31013288, 2019). "The genes GEM (GTP-binding protein GEM) and PPP1R13L (Protein Phosphatase 1 Regulatory Subunit 13 Like) are interesting target genes of NF-κB as they can act as novel targets for obesity or related syndrome." (PMID 31013288, 2019). "One of the interesting highlights of the study is two promising genes GEM, and PPP1R13L were predicted as novel potential biomarkers of obesity or related syndrome as they share characteristics of known obesity genes in the prioritized list." (PMID 31013288, 2019). "Also, two promising genes GEM and PPP1R13L were predicted as novel potential biomarkers of obesity or related syndrome as they share characteristics of known obesity genes in the prioritized list." (PMID 31013288, 2019). "Interestingly, GEM and PPP1R13L were predicted as novel genes which may act as potential target or biomarkers of obesity as they occur with other 21 target genes with known obesity relationship." (PMID 31013288, 2019).
tumor (59 papers, 2007 to 2026). "PPP1R13L knockdown resulted in reduced tumor growth, with significantly decreased terminal tumor mass and size, demonstrating that PPP1R13L knockdown effectively suppressed the development of SiHa-derived tumors in vivo." (PMID 40014097, 2025). "In this study, we utilized public databases to reveal the correlation between PPP1R13L and tumor progression pathways." (PMID 40014097, 2025). "Accordingly, it was generally believed that PPP1R13L as a novel oncogene highly expressed in a variety of tumor cells." (PMID 38952985, 2024). "Next, we performed a survival analysis using tumor tissue specimens from the 112 GC patients and found that, among the three genes, only PPP1R13L showed a significant correlation with both OS and DFS in these patients." (PMID 35717675, 2022). "While circHIPK3 (homeodomain interacting protein kinase 3) would influence the proliferation of tumor cells through genes, including protein phosphatase 1 regulatory subunit 13 like (iASPP) by working as the sponge of miR-124 to inhibit miR-124 activity." (PMID 28928231, 2017). "In PC cell lines, XIST and miR-140/miR-124, two tumor-associated miRNAs, could inversely regulate each other, respectively; miR-140/miR-124 could bind to XIST and the 3’UTR of PPP1R13L, respectively." (PMID 29371940, 2017). "By real-time qPCR, we further examined the expression of selected genes (Pkm, Ppp1r13l, Vamp3, Ctnnb1, Tbc1d4, Ppp1r21, C1qtnf9, Fgf3 and Efemp2) that are known to be involved in the tumor development or potentially relevant for establishment of malignant transformation." (PMID 29073177, 2017). "In this study, scRNA‐seq results revealed that the expressions of GLS, PPP1R13L, MYB, and YAP1 were significantly elevated in tumor epithelial cells." (PMID 41152153, 2025). "The remaining four PCRGs (ASPDH1, PPP1R13L, PMAIP1, and KLHL35) showed higher expression levels in tumor tissues than in pericardial tissues." (PMID 37190215, 2023). "RT‐qPCR and immunohistochemical (IHC) staining of tumor sections were used to analyze the expression of TMEM44‐AS1 and PPP1R13L in the xenograft tumors." (PMID 35717675, 2022).
cancer (58 papers, 2007 to 2025). A tumor composed of atypical neoplastic, often pleomorphic cells that invade other tissues. "PPP1R13L was predicted to be associated with cancer progression and response to therapy, and sqamous cell carcinoma was more sensitive to adjuvant therapy than adenocarcinoma." (PMID 29108262, 2017). "We found that both normal and cancer tissues exhibit similar expression patterns for PPP1R13L and p63; they are frequently highly expressed in tissues such as skin and mucosa, including normal cervical and cancer tissues." (PMID 40014097, 2025). "Several epidemiological studies had demonstrated that PPP1R13L rs1005165 and CD3EAP rs967591 were related to an individual’s susceptibility to cancer." (PMID 26681190, 2015). "Studying one marker at a time, we found a region spanning the gene RAI (alias PPP1R13L or iASPP) and the 5' portion of XPD to be associated with this cancer." (PMID 18588689, 2008). "PPP1R13L is positively expressed in adjacent normal tissues but is even higher in cancer tissues." (PMID 40014097, 2025). "In addition, an integrated haplotype analysis of 5 SNPs in ERCC1, CD3EAP, and PPP1R13L on 19q13 was performed to explore higher LD with the cancer‐related SNP." (PMID 30453383, 2018). "Both PPP1R13L rs1970764 in block 3 and CD3EAP rs967591 in block 5 were important constituents of the previously identified “high-risk haplotype” associated with increased risk of several cancers among Caucasian." (PMID 27183913, 2016). "In addition, the PPP1R13L, CD3EAP and ERCC1 polymorphisms are in linkage disequilibrium with each other in cancers, and XPC rs2228001 and rs2279017 and XPF rs4781560, which are located in the same region, had significant linkage disequilibrium." (PMID 26681190, 2015). "To further verify the validity of the data, we used the GEPIA database to validate the expression of DSP, PPP1R13L and ANXA8 in human cancers and normal cervix." (PMID 38952985, 2024). "To further verify the validity of the data, we used GEPIA database to validate the expression of DSP, PPP1R13L and ANXA8 in human cancers and normal cervix." (PMID 38952985, 2024). "Linkage disequilibrium-mapping studies in Caucasians have indicated anassociation of Chr19q13.3 sub-region spanning ERCC2, PPP1R13L, CD3EAP and ERCC1 with several cancers." (PMID 27183913, 2016). "Among the biomarker gene pairs, PPP1R13L, EGFR, IL15RA, or PIM1 are acting in the cancer core pathways." (PMID 26916442, 2016). "Additionally, through the Human Protein Atlas website, we compared the expression of PPP1R13L, PTEN, and p63 in 20 cancer pathology tissue slides and RNA expression across 55 types of normal tissues." (PMID 40014097, 2025). "Moreover, we used GEPIA database to validate the expression of DSP, PPP1R13L and ANXA8 in human cancers and normal cervix." (PMID 38952985, 2024). "Among them are genes involved in cell adhesion/migration processes (PEPD), migratory potential of cancer cells (ACTN1), ECM (LTBP2, PRG4, ADGRL1, CD9), or in metabolic processes (LDHD, ALDH7A1), as well as proto-oncogenes or their ligands/inhibitors (FYN, PPP1R13L)." (PMID 30838002, 2019).
PPP1R13L also shares sentences with these, for which no sentence is quoted: glioblastoma (11 papers); prostate carcinoma (8); acute leukemia (7); leukemia (7); hepatocellular carcinoma (6); ovarian carcinoma (5); bladder cancer (4); pancreatic cancer (4); cervical adenocarcinoma (3); cutaneous melanoma (3); gastric cancer (3); oral cavity squamous cell carcinoma (3); pancreatic tumor (3); Stroke (3); xeroderma pigmentosum (3); arrhythmogenic right ventricular cardiomyopathy (2); Cerebral ischemia (2); chordoma (2); chronic pancreatitis (2); dilated cardiomyopathy (2); head and neck squamous cell carcinoma (2); ischemic stroke (2); liver cancer (2); lung squamous cell carcinoma (2); metastatic disease (2); ovarian clear cell cancer (2); pancreatic ductal adenocarcinoma (2); acute lung injury (1); acute myeloid leukemia (1); acute pancreatitis (1).
A further 46 diseases each share a sentence with PPP1R13L in 1 paper.